LGALS1 (galectin 1)
Diseases named in the same sentence as LGALS1 in open-access papers (continued):
Sharing a sentence is not in itself a finding about the gene and the disease.
prostate carcinoma (18 papers, 2010 to 2025). A carcinoma that arises from epithelial cells of the prostate gland. "In 2014, GOLGB1 was reported to enhance susceptibility to galectin-1 in prostate cancer, thereby inducing cellular apoptosis." (PMID 40657366, 2025). "We found that Galectin-1 is upregulated in enzalutamide-resistant prostate cancer cells and promotes resistance by regulating androgen receptor expression." (PMID 39941722, 2025). "The preliminary in vitro and in vivo results in a PC3 cell line and tumor model indicate that the tumor specificality of the therapeutic agent(s) can be increased by targeting galectin-1 and galectin-3, known for their overexpression in prostate cancer." (PMID 37445799, 2023). "Galectin-1 expression is also enhanced in stromal and endothelial cells, which are treated by conditioned media derived from ovarian and prostate cancer cells, indicating the role of galectin-1 in the crosstalk of tumor cells with inflamed vasculature." (PMID 36873388, 2023). "The studies in prostate cancer have mainly focused on Galectin-1 and Galectin-3, but the importance of Galectin-4, Galectin-7, Galectin-8, and Galectin-9 has also been highlighted (reviewed by 11, 33, 34)." (PMID 36936148, 2023). "Mac-2binding protein (Mac-2BP) plays a role in cell–cell and cell–matrix adhesion by binding to Galectin-1, Galectin-3, fibronectin and collagen, which is a candidate biomarker in nonalcoholic fatty liver disease diagnosis and prostate cancer diagnosis." (PMID 36010914, 2022). "Until now, protein S expression has been studied in oral squamous cell carcinoma and prostate cancer, and galectin-1 expression has been identified in renal clear cell carcinoma." (PMID 33453410, 2021). "Rabinovich and colleagues identified that prostate cancer shows a unique galectin expression profile during cancer progression, and showed that galectin-1 is uniquely expressed at high levels in advanced prostate cancer." (PMID 31151317, 2019). "The galectin-1/glycodendrimer nanoparticle aggregates were then used to inhibit the galectin-1 induced aggregation of DU145 human prostate carcinoma cells." (PMID 26124876, 2015). "The first reports about expression galectin-1 and -3 in prostate cancers showed that galectin-1 was expressed in most cases of all four histologic types." (PMID 23658855, 2010). "Interestingly, one group has previously indicated that LGALS1 inhibited cell proliferation and induced apoptosis in human colorectal 28 and prostate cancer cells." (PMID 32047564, 2020). "This makes galectin-1 a potential target of angiogenesis therapy in advanced prostate cancer." (PMID 31151317, 2019). "Galectin-1 downregulation can inhibit invasion in prostate cancer." (PMID 28841682, 2017). "Validation at the protein level confirmed that upregulation of GCNT1 in prostate cancer cells promotes loss of Galectin-1 and analysis of The Cancer Genome Atlas Prostate Adenocarcinoma (TCGA PRAD) cohort revealed a correlation between the GCNT1 and LGALS1 genes in clinical prostate cancer tissue." (PMID 37813880, 2023). "On the other hand, recent study using biopsy samples, representing different stages of the primary prostate cancer, showed that prostate specific membrane antigen (PSMA), Galectin-1 and Galectin-3 are the most abundantly expressed glycoproteins." (PMID 36936148, 2023). "Increased gene body methylation in prostate cancer correlating with decreased expression of mRNA and protein expression was identified on GNAO1, LGALS1, TNS1, and PPAP2B." (PMID 29563510, 2018). "After determining that lactose-functionalized dendrimers 1–4 reproducibly nucleate formation of galectin-1 aggregates that are quite homogeneous, we used these nanoparticles in cellular aggregation assays with galectin-1 and DU145 human prostate cancer cells." (PMID 26124876, 2015).
cervical cancer (17 papers, 2011 to 2025). A primary or metastatic malignant neoplasm involving the cervix. "In this study, we observed that LGALS1 was upregulated in cervical cancer tissues and cell lines, and it was significantly associated with aggressive behavior of cervical squamous carcinoma." (PMID 32047564, 2020). "The aim of this study was to determine the phenotype of galectin-1, -3 and -9 expressing cells and the association with clinico-pathological parameters in cervical cancer." (PMID 26066796, 2015). "Galectin-1 and integrin α5β1 may be implicated in the development of chemoresistance in cervical cancer via suppressing apoptosis." (PMID 28842515, 2017). "Additionally, the phenotype of cells expressing galectin-1, -3 and -9 and the association with clinico-pathological parameters in cervical cancer has been previously investigated." (PMID 28355349, 2017). "It is also suggested from our findings that galectin-1 and integrin α5β1 may be implicated in the development of chemoresistance in cervical cancer via suppressing apoptosis." (PMID 28842515, 2017). "Notably, our previous proteomic study demonstrated that the expression of LGALS1 is significantly reduced after neoadjuvant chemotherapy treatment in cervical cancer patients, which may be associated with neoadjuvant chemotherapy exposure and response." (PMID 32047564, 2020). "The expression of PIBF and Galectin-1 in precancerous tissues of cervical cancer was determined by the immunohistochemical method and ELISA method, and their clinical significance was analyzed." (PMID 41210885, 2025). "In our previous research, LGALS1 was uncovered to promote cell proliferation and inhibit cell apoptosis of cervical cancer." (PMID 33854625, 2021). "The level of Bcl-2, MMP-2, MMP-9, Fascin, and Erzin expression was significantly upregulated in cervical cancer cells with LGALS1 overexpression, while converse results were obtained in LGALS1 knockdown cancer cells." (PMID 32047564, 2020). "The objective of this study is to investigate the effects of LGALS1 expression on biological behaviors of cervical cancer cells." (PMID 32047564, 2020). "Specifically, Ezrin is increased in cervical cancer cells (SiHa and C33A) when Galectin-1 (LGALS1) is overexpressed." (PMID 33240887, 2020). "Up to date, several clinicopathological studies have revealed an independent role of LGALS1 for predicting tumor progression and poor survival of cervical cancer patients 17-19." (PMID 32047564, 2020). "More importantly, the influence of LGALS1 on the tumor growth of cervical cancer in vivo was further studied." (PMID 32047564, 2020). "The mean IHC scores of LGALS1 in cervical cancer and normal cervical tissues were 8.40 ± 2.23 and 1.15 ± 0.81, respectively." (PMID 32047564, 2020). "To further investigate the effects of LGALS1 on multiple biological functions of human cervical cancer cells, we employed lentivirus-mediated vectors to successfully overexpress and knockdown endogenous LGALS1 in SiHa and C33A cell lines." (PMID 32047564, 2020). "Significantly higher expression of LGALS1 was exhibited in cervical cancer tissues (mainly in the cytoplasm) than normal cervical samples, while the latter showed only weak expression of LGALS1." (PMID 32047564, 2020). "Strikingly, our study used shRNA to downregulate LGALS1 more stably and explored several signaling molecules related to the biological behavior of cervical cancer cells, which strengthened the results of this study." (PMID 32047564, 2020). "Western blot analysis was performed to evaluate the efficacy of lentivirus-mediated upregulation or downregulation of LGALS1 in cervical cancer cells." (PMID 32047564, 2020). "LGALS1 overexpression in cervical cancer cell lines resulted in the promotion of cell proliferation, migration and invasion, as well as suppression of cell apoptosis." (PMID 32047564, 2020). "In vivo study also showed that LGALS1 overexpression facilitated tumor growth of cervical cancer cells." (PMID 32047564, 2020).
cervical cancer (continued). "In this review, we mainly focus on the role of galectins, especially galectin-1, galectin-3, galectin-7, and galectin-9 in cervical cancer, and provide theoretical basis for potential targeted treatment of cervical cancer." (PMID 29854732, 2018). "Galectin-1, a radioresistance marker, was found in our previous study to be a prognostic factor for cervical cancer." (PMID 29378529, 2018). "The expression of galectin-1 and integrin α5β1 in stromal and tumor cells was significantly down-regulated in postchemotherapy cervical cancer tissues." (PMID 28842515, 2017). "Prechemotherapy cervical cancer tissues consistently showed moderate or intense positive staining of galectin-1 and integrin α5β1 in tumor cells, while postchemotherapy tissues consistently showed weak or moderate positive staining in tumor cells." (PMID 28842515, 2017). "In the present study, we found that the expression of galectin-1 was down-regulated both in cervical stromal cells and cervical cancer cells after chemotherapy, suggesting galectin-1 involved in chemotherapy response in cervical cancer." (PMID 28842515, 2017). "The mRNA levels of galectin-1, integrin α5, and integrin β1 were much higher in cervical cancer tissues than that in normal cervical tissues." (PMID 28842515, 2017). "In agreement with previous data, we found that galectin-1 mRNA was much higher in cervical cancer samples compared with normal cervical tissues." (PMID 28842515, 2017). "Our current study detected galectin-1 expressed both in tumor cells and stromal cells, moreover, galectin-1 accumulated more frequently in stromal cells than its in tumor cells of cervical cancer, which is consistent with previous immunohistochemical studies." (PMID 28842515, 2017). "Galectin-1 inhibition by siRNA or galectin-1 antibody suppressed the growth of cervical cancer both in vitro and in vivo." (PMID 28842515, 2017). "Galectin-1 has been widely reported to be overexpressed in cervical cancer cell lines and cervical cancer samples." (PMID 28842515, 2017). "Expression of galectin-1 in the stroma of cervical cancer has also been correlated with higher histopathological grade and lymph node metastasis." (PMID 26066796, 2015). "Galectin-1, -3 and -9 have become the focus of different research groups, but their expression and function in cervical cancer is still unclear." (PMID 26066796, 2015). "RACK1 promotes cervical cancer invasion and lymph node metastasis through galectin-1." (PMID 37828084, 2023). "It has been reported that RACK1 could participate in the lymphangiogenesis and LN metastasis of cervical cancer in a Galectin-1-dependent manner, suggesting that targeting RACK1 may be a promising strategy." (PMID 36658304, 2023). "Moreover, our previous study using proteomics profiling has also confirmed that expression of LGALS1 was significantly decreased in cervical cancer patients after neoadjuvant chemotherapy administration." (PMID 32047564, 2020). "Due to that downregulation of LGALS1 might contribute to the interference with tumor progression, LGALS1 could be evolved as a promising therapeutic target in the treatment of cervical cancer." (PMID 32047564, 2020). "Furthermore, we also investigated the effect of LGALS1 overexpression and knockdown on the proliferation, apoptosis, and migratory and invasive capabilities of cervical cancer cells and the related proteins in vitro." (PMID 32047564, 2020). "Xenograft mouse model of cervical cancer was generated to explore whether LGALS1 overexpression could promote tumor growth in vivo." (PMID 32047564, 2020). "We first found galectin-1 to be involved in radioresistance in cervical cancer." (PMID 29378529, 2018). "Furthermore, galectin-1 is an independent prognostic factor for local recurrence and survival in stage I–II cervical cancer patients undergoing definitive radiation therapy." (PMID 28842515, 2017). "Another protein detected by us as a member of the "central core of cervical cancer" was galectin-1." (PMID 21696634, 2011).
cervical cancer (continued). "Furthermore, LGALS1 downregulation had the opposed results in cervical cancer cells." (PMID 32047564, 2020). "Taken together, this study revealed that LGALS1 is overexpressed in cervical cancer patients and cervical cancer cells, while LGALS1 downregulation had the opposed results in cervical cancer cells, indicating that LGALS1 may play an oncogenic role in the cervical carcinogenesis." (PMID 32047564, 2020). "Moreover, LGALS1 overexpression promoted cervical cancer growth in mice by in vivo study." (PMID 32047564, 2020). "Moreover, LGALS1 overexpression also promoted the tumor growth of cervical cancer in vivo." (PMID 32047564, 2020). "Previous literature verified that RACK1 could promote cervical cancer lymphangiogenesis and lymph node metastasis by augmenting Galectin-1-induced downstream FAK, and AKT signaling in cervical cancer cells." (PMID 36658304, 2023). "Cervical cancer cells could enhance the remodeling of lymphatic vessels by secreting pro-lymphangiogenic growth factors, such as the VEGF-C and Galectin-1." (PMID 36658304, 2023). "A significant difference in LGALS1 expression was observed between cervical cancer and adjacent non-tumor cervical tissues (P <0.01)." (PMID 32047564, 2020). "In the current study, we explored the expression of LGALS1 protein in cervical cancer tissues and cells compared to adjacent non-tumor tissues and epithelial cells of cervix, respectively." (PMID 32047564, 2020). "In our study, overexpression of LGALS1 was also observed in human cervical cancer tissues as compared with matched non-tumor samples using IHC staining, corresponding with previous reports 17-19." (PMID 32047564, 2020). "To understand the expression of LGALS1 in cervical cancer, we conducted IHC analyses of 20 cervical cancer specimens and matched non-tumor tissues in this study." (PMID 32047564, 2020). "Nevertheless, the function of LGALS1 on biological behavior in cervical cancer has not been extensively investigated yet." (PMID 32047564, 2020). "However, in contrast to cervical cancer, GBM exhibits high galectin-1 expression and is radioresistant." (PMID 29378529, 2018). "The expression of galectin-1 and integrin α5β1 in prechemotherapy cervical cancer tissues between chemotherapy responders and non-responders was analyzed by immunohistochemistry." (PMID 28842515, 2017). "Moreover, we did not explore how LGALS1 promoted the tumorigenesis and progression of cervical cancer and the potential signaling pathways, which need to be elucidated in the future." (PMID 32047564, 2020). "However, the research focusing on the role of LGALS1 in cervical cancer cells has not been extensively conducted." (PMID 32047564, 2020). "However, the role of LGALS1 in cervical cancer is still not fully elucidated." (PMID 32047564, 2020).
leukemia (15 papers, 2015 to 2025). A malignant (clonal) hematologic disorder, involving hematopoietic stem cells and characterized by the presence of primitive or atypical myeloid or lymphoid cells in the bone marrow and the blood. "This study therefore highlighted that high LGALS1 expression in leukemia stem cells is a significant risk factor for cancer development." (PMID 40178639, 2025). "In leukemia, LGALS1 upregulates the expression of genes involved in lipid uptake (such as CD36) and de novo lipogenesis (such as PPARγ, FASN, and ACC), thereby enhancing lipid accumulation." (PMID 40881692, 2025). "LGALS1 repression also inhibited leukemia stem cell and leukemia cell proliferation and increased cell apoptosis in vitro." (PMID 40178639, 2025). "LGALS1 promoted cell proliferation and inhibited cell apoptosis via shRNA of LGALS1 and a specific inhibitor of LGALS1 in leukemia cells (HEL and THP1) and LSCs in vitro, and enhanced AML progression in vivo." (PMID 38965225, 2024). "We also determined LGALS1 expression in a set of leukemia cells, and found a relative stronger endogenous LGALS1 was seen in HEL, THP1, MV411, and NB4 cells." (PMID 38965225, 2024). "By performing network analysis based on physical interactions and co-expression, we demonstrated that the upregulated genes LGALS1, S100A10, EMP3, and S100A4 in the residual leukemia-like cells were involved in a functional module with LGALS1 as a hub gene." (PMID 36543880, 2023). "There is increasing evidence that Galectin-1 and Galectin-3 are involved in the protective cross-communication between leukemia cells and the bone marrow microenvironment." (PMID 36430839, 2022). "We analyzed an RNA microarray gene expression data set of such samples (GSE110104) to determine if Lgals1 and Lgals3 are endogenously expressed in the mouse leukemia cells." (PMID 36430839, 2022). "The involvement of galectin-1 in mechanisms of erythropoiesis was demonstrated in a model of human leukemia cell line K562, which constitutively expresses this lectin in cytoplasm." (PMID 32731422, 2020). "Herein, galectin-1 was identified as a candidate modulator of MDR1 by proteomic analysis of a model system of leukemia cell lines with a gradual increase of MDR1 expression and drug resistance." (PMID 27050374, 2016). "Therefore, we refine the effect of LGALS1 on the lipid uptake and de novo lipogenesis in LSCs and leukemia cells." (PMID 38965225, 2024). "While, the enhancement of LGALS1 on AML progression lacks of sufficient evidence, and whether LGALS1 regulates lipid metabolism in leukemia remains unknown." (PMID 38965225, 2024). "Thus, LGALS1 promotes cell proliferation and inhibits cell apoptosis in LSCs and leukemia cells in vitro." (PMID 38965225, 2024). "As leukemia cells absorb lipid from microenvironment through LGALS1, which may lead to less uptake of fatty acids for immune cells to maintain their function." (PMID 38965225, 2024). "Galectin-1 signals in the same BCP-ALL samples showed little variation, regardless of whether they had been co-cultured with wt or Galectin-1 OP9 KO cells, suggesting most of the Galectin-1 was leukemia cell endogenous." (PMID 36430839, 2022). "Indeed, inhibition of leukemia patients’ serum galectin-1 by OTX008 abrogates IL-10 production by dendritic and T cells, implying this molecule prevents immune deactivation." (PMID 34572756, 2021). "Additionally, high Galectin-1 expression was previously reported using immunohistochemistry in Hodgkin lymphoma samples, and in mixed lineage leukemia-rearranged BP-ALL cells by FACS and Western blot." (PMID 29580262, 2018). "LGALS1 belongs to the galectins family of beta-galactoside-binding proteins that modulate cell-cell and cell-matrix interactions, its expression correlates with tumor cell motility and invasiveness, and is up-regulated in leukemia." (PMID 27447550, 2016). "While, whether LGALS1 regulates lipid metabolism in leukemia cells remains unknown." (PMID 38965225, 2024).